HMGN1 (high mobility group nucleosome binding domain 1)
Diseases named in the same sentence as HMGN1 in open-access papers (continued):
Sharing a sentence is not in itself a finding about the gene and the disease.
Rett syndrome (2 papers, 2014 to 2020). A severe neurodevelopmental disorder affecting the central nervous system.
type 1 diabetes (2 papers, 2022 to 2023). "Based on the previous research on the mechanism of HMGN1 in inflammation, we have shown that HMGN1 can induce inflammatory or immune responses by triggering TLR4-dependent signaling pathways in a type 1 diabetes mice." (PMID 36691481, 2023).
asthma (1 paper, 2020). "Concretely, four genes (ATF7IP, SLC43A3, AKAP7, HMGN1) were found to be correlated to pathogenesis or treatment of asthma in immune." (PMID 32948203, 2020).
B cell lymphoblastic leukemia (1 paper, 2022). "Furthermore, HMGN1, expressed on HSA21 and has recently been shown to have a role in B cell lymphoblastic leukemia, might disrupt chromatin in DS progenitor cells, leading to abnormal PAX6 binding." (PMID 36313423, 2022).
embryonal carcinoma (1 paper, 2019). A non-seminomatous malignant germ cell tumor characterized by the presence of large germ cells with abundant cytoplasm resembling epithelial cells, geographic necrosis, high mitotic activity, and pseudoglandular and pseudopapillary structures formation. "The results of the present work demonstrate that the loss of HMGN1 or HMGN2 compromises the ability of embryonal carcinoma cells, and the neural stem cells derived from them, to self-renew accurately and maintain pluri/multipotency." (PMID 31831052, 2019). "We show that loss of Hmgn1 or Hmgn2 in pluripotent embryonal carcinoma cells leads to increased levels of spontaneous neuronal differentiation." (PMID 31831052, 2019). "CRISPR mutagenesis was used to create clonal derivatives of murine P19 embryonal carcinoma cells in which HMGN1 or HMGN2 protein expression was abolished." (PMID 31831052, 2019). "We conclude that HMGN1 and HMGN2 maintain the identity of pluripotent embryonal carcinoma cells by optimising the pluripotency transcription factor network and protecting the cells from precocious differentiation." (PMID 31831052, 2019). "In this study, we have investigated the role of HMGN1 and HMGN2 in P19 embryonal carcinoma stem cells." (PMID 31831052, 2019).
glioblastoma multiforme (1 paper, 2025). "Furthermore, data from the UALCAN database demonstrated that the HMGN1 protein was over-expressed in the malignant colon, breast, glioblastoma multiforme, LIHC, LUAD, and ovarian cancer tissues compared to the healthy tissue samples." (PMID 38310387, 2025).
head and neck squamous cell carcinoma (1 paper, 2018). A squamous cell carcinoma that arises from any of the following anatomic sites: lip and oral cavity, nasal cavity, paranasal sinuses, pharynx, larynx, and salivary glands. "In the present study, we investigated the expression and significance of high mobility group box 1 (HMGB1), HMG nucleosome-binding protein 1 (HMGN1), the receptor programmed cell death 1 (PD-1) and its ligand programmed cell death ligand 1 (PD-L1) in head and neck squamous cell carcinoma (HNSCC)." (PMID 30619746, 2018).
herpes simplex infection (1 paper, 2022). "Apart from this similarity, different virus infection pathways owned their unique genes, with STAT1,RSAD2 and IRF9 in the influenza A pathway,IL-2RA,IL-2RB and CD40 in the HTLV-1 infection pathway, HCFC1, MAP3K7, SOCS3, IRF9, HMGN1, and FAS in the herpes simplex infection pathway." (PMID 35795668, 2022).
kidney damage (1 paper, 2023). "The next analysis investigated whether PM2.5 exposure causes kidney damage via HMGN1-KIM-1." (PMID 37671359, 2023). "The expressions of high mobility group nucleosome binding protein 1 (HMGN1) and kidney injury molecule 1 (KIM-1) that are associated with kidney damage increased in kidney after PM2.5 exposure." (PMID 37671359, 2023). "We found that PM2.5 aggravated kidney damage and abnormal lipid metabolism, which were correlated with increased expression of HMGN1 and KIM-1 expression." (PMID 37671359, 2023). "Our previous study found that HMGN1 expression was elevated in DKD and kidney damage and can cause increased KIM-1 expression (J Yu, J Da, F Yu, J Yuan, Y Zha, 2022, unpublished data)." (PMID 37671359, 2023).
lipid metabolism disorders (1 paper, 2023). "The present study aims to investigate the role of PM2.5 in kidney damage, especially lipid metabolism disorders and to determine whether the underlying mechanisms of action are associated with HMGN1-KIM-1 in the kidneys of DKD mice." (PMID 37671359, 2023). "It indicated that HMGN1-KIM-1 may aggravate the lipid metabolism disorder in the kidney." (PMID 37671359, 2023).
lung adenocarcinoma (1 paper, 2024). A carcinoma that arises from the lung and is characterized by the presence of malignant glandular epithelial cells. "In summary, our systematic analysis positions HMGN1 as a diagnostic and prognostic marker for lung adenocarcinoma." (PMID 38710740, 2024). "The indispensable role of HMGN1 in HRR prompted us to test the potential of HMGN1 inhibition to sensitize lung adenocarcinoma cells to DNA damage agents, which is frequently applied in clinical setting." (PMID 38710740, 2024). "This study proposes HMGN1 as a novel prognostic biomarker and a promising target for chemotherapy in lung adenocarcinoma." (PMID 38710740, 2024). "To investigate the function of HMGN1 in lung adenocarcinoma, we first explored the potential co-expression genes of HMGN1 using the weighted gene co-expression network analysis (WGCNA) followed by GO analysis." (PMID 38710740, 2024). "Given that double-strand break (DSB) is the most lethal form of DNA damage and HMGN1 function in DSB repair remains largely unknown, above analysis prompted us to test whether HMGN1 is involved in DSB repair in lung adenocarcinoma cells." (PMID 38710740, 2024). "Therefore, how HMGN1 ultimately participates in the progression of lung adenocarcinoma remains to be explored." (PMID 38710740, 2024). "Given the pivotal role of HMGN1 in peri-tumor infiltration of lymphocytes, combining HMGN1 targeting with immunotherapy might achieve better therapeutic outcomes for lung adenocarcinoma." (PMID 38710740, 2024). "Finally, the roles of HMGN1 in the ATR-ChK1 and DNA double-strand break (DSB) repair pathways was manifested in vitro in lung adenocarcinoma cells." (PMID 38710740, 2024).
microcephaly (1 paper, 2023). A congenital or acquired developmental disorder in which the circumference of the head is smaller than normal for the person's age and sex. "In Xenopus laevis embryos, injection of HMGN1 protein causes body axis curvature, cyclopia and microcephaly, which are all phenotypes associated with aberrant SHH signaling." (PMID 36995257, 2023).
myocardial infarction (1 paper, 2025). Gross necrosis of the myocardium, as a result of interruption of the blood supply to the area, as in coronary thrombosis. "Additionally, MRPS23 and HMGN1 contribute to mitochondrial dysfunction and stress response regulation, exacerbating cell damage and inflammation, ultimately promoting heart attack (myocardial infarction) through increased ROS and DNA damage." (PMID 40775796, 2025).
osteosarcoma (1 paper, 2020). A usually aggressive malignant bone-forming mesenchymal neoplasm, predominantly affecting adolescents and young adults. "To confirm that this lack of phenotype is not specific to osteosarcoma cells, we generated additional HMGN1/HMGN2-dKO cells in hTERT-immortalized human retinal pigment epithelial cells (RPE1) by CRISPR-Cas9-mediated genome editing." (PMID 32152397, 2020).
pancreatic adenocarcinoma (1 paper, 2025). "The HMGN1 expression was significantly and positively linked with several immune-related genes in KIRC, HNSC, LIHC, and pancreatic adenocarcinoma (PAAD) cells." (PMID 38310387, 2025).
Skin Cutaneous Melanoma (1 paper, 2025). "The HMGN1 gene expression levels were also evaluated in 21 tumors at different stages and significant differences were noted in the HMGN1 expression levels in KICH, ACC, KIRC, THCA, and Skin Cutaneous Melanoma (SKCM)." (PMID 38310387, 2025).
Stroke (1 paper, 2014). Sudden impairment of blood flow to a part of the brain due to occlusion or rupture of an artery to the brain. "Interestingly, TS down-regulated Hmgn1 in motor cortex and offset the effects of cumulative stress on stroke recovery." (PMID 24651125, 2014).
testicular germ cell tumor (1 paper, 2025). A germ cell tumor arising from the testis. "The findings indicated that Kidney Chromophobe (KICH) exhibited the lowest HMGN1 expression level, while Testicular Germ Cell Tumors (TGCT) showed the highest HMGN1 expression levels." (PMID 38310387, 2025).
testicular tumor (1 paper, 2025). "In addition to SPTBN4, 31 other molecules were analyzed, revealing potential testicular tumor markers such as TPI1, HMGN1, UGCG, NCL, SET, and EIF3K." (PMID 40321316, 2025).
uterine carcinosarcoma (1 paper, 2025). A usually aggressive malignant neoplasm arising from the uterine corpus and less often the cervix. "Additionally, few immune-related genes were found to be associated with HMGN1 in different cancers such as ACC, CHOL, ESCA, KICH, MESO, PCPG, and Uterine Carcinosarcoma (UCS)." (PMID 38310387, 2025).
tumor (26 papers, 2008 to 2025). "In a recent study on patients with head and neck carcinoma, it was observed that cytoplasmic localization and secretion of HMGN1 was associated with the recruitment of tumor infiltering lymphocytes." (PMID 31936777, 2020). "In summary, HMGN1 is a highly effective tumor diagnostic marker." (PMID 38310387, 2025). "In addition, Birger and colleagues (2006) identified significantly down-regulated genes located in the area of the common deletion site, of which at least one, HMGN1, has been associated with tumor growth in mice and primary mouse embryonic fibroblast cell lines." (PMID 18694509, 2008). "Further research is warranted to validate the presence of HMGN1 expression in supplementary tumor samples and establish a connection between HMGN1 levels and the survival rates of cancer patients." (PMID 38310387, 2025). "Since both HMGB1 and HMGN1 are known to trigger DC maturation, these results substantiate the notion that DAMPs/alarmins released by tumor cells in response to LTX-315 treatment contribute to DC maturation." (PMID 38545099, 2024). "The expression of HMGN1 in all tumor stages (I–IV) was significantly higher than that in normal group." (PMID 38710740, 2024). "Analysis of gene expression of LUAD and matched adjacent non-tumor tissues from three cohorts showed consistent up-regulation of HMGN1 in LUAD across all cohorts, with HMGN5 down-regulated in two of them." (PMID 38710740, 2024). "Here, the authors generate alarmin HMGN1-attached tumour exosomes which significantly improve therapy efficacy by boosting DC activation in several preclinical mouse models." (PMID 32286296, 2020). "Upon exposure to ionizing radiation, the tumor burden and mortality in Hmgn1−/− mice are higher as compared to their wild-type littermate mice." (PMID 31936777, 2020). "The anti-tumor effects of HMGN1, anti-CD4 depleting antibody, and their combined treatment were monitored in the Colon26 or the B16F10 subcutaneous murine models." (PMID 30696484, 2019). "Our study represents a novel combination therapy of low-dose HMGN1 with αCD4 to exert robust anti-tumor effects in mice." (PMID 30696484, 2019). "We used immunohistochemistry to examine the subcellular localization and expression levels of HMGB1 and HMGN1, as well as tumor CD3+, CD8+, FOXP3+ lymphocyte infiltration, and the expression of immune inhibiting molecules PD-1/PD-L1." (PMID 30619746, 2018). "When released by tumor cells, extracellular HMGN1 function as a Th1-polarizing alarmin that attracts CD8+ CTLs and promotes the induction of adaptive antitumor immune responses." (PMID 30619746, 2018). "In our present work, we found that 31 out of 81 patients had positive cytoplasmic expression of HMGN1 in tumor tissue." (PMID 30619746, 2018). "Taken together, there were totally 16 patients whose tumor tissues were harboring HMGN1 cytoplasmic expressed and PD-L1 positive tumor cells, as well as PD-1 positive tumor infiltrating lymphocytes (TILs)." (PMID 30619746, 2018). "We are currently investigating the means of overcoming this limitation by using nanoparticles for the delivery of R848 and HMGN1 into tumor tissues upon systemic administration." (PMID 28881713, 2017). "As anticipated, CY alone slightly reduced the rate of growth of CT26 Hepa1-6 tumors, while four rounds of treatment with HMGN1 and R848 showed more significant inhibition of tumor growth." (PMID 28881713, 2017). "When 5 Balb/c mice bearing large Renca tumors were treated with i.p. injection CY and i.t. injection of R848 + HMGN1, four were cured and became tumor-free for more than 2 months." (PMID 29079801, 2017). "We are investigating means of overcoming this limitation by using nanoparticle platforms for the delivery of R848 and HMGN1 since many nanoparticle delivery systems can deliver payload into tumor tissues upon systemic administration." (PMID 29079801, 2017).
tumor (continued). "Hepa1-6 tumor bearing mice were then treated with i.t. injection of HMGN1 and R848 into the larger tumors on the right flank and one dose of intraperitoneal (i.p)." (PMID 28881713, 2017). "The i.t. route was chosen to promote the activation of APCs infiltrating tumor tissues by HMGN1, particularly tDCs." (PMID 29079801, 2017). "Furthermore, the probable involvement of HMGN1 in the anti-tumor immune response was also determined." (PMID 38310387, 2025). "Furthermore, HMGN1 expression was linked to microsatellite instability (MSI) and tumor mutational burden (TMB) across diverse tumor types." (PMID 38310387, 2025). "Indeed, several studies suggest that HMGN1 manifests anti-tumor effects by promoting DNA repair and genome stability." (PMID 38710740, 2024). "Additionally, high HMGN1 levels correlate with increased peri-tumor infiltration of lymphocytes in Her2-positive breast cancer." (PMID 38710740, 2024). "HMGN1 and HMGN2 affect DNA damage repair and organ development and maturation by regulating the expression of genes or proteins, and are also implicated in tumor immune responses." (PMID 36568211, 2022). "HMGN1 is an alert protein contributing to the extracellular production of LPS-induced innate and antigen-specific as well as Th1-polarized adaptive immune responses, which play a key role in cell-mediated tumor immune responses." (PMID 36568211, 2022). "We have indeed observed that HMGN1 expression is lowered in HCC tumor than para-tumoral tissues." (PMID 32286296, 2020). "Moreover, low doses of HMGN1 with anti-CD4 depleting antibody promoted the expansion of anti-tumor CD8 T cells by rescuing them from exhaustion." (PMID 31936777, 2020). "In the present study, we observed that those mice receiving intraperitoneal administration of low-dose HMGN1 with αCD4 had an increasing number of tumor-infiltrating CD8+ T cells with the less exhausted phenotypes and the capacity to produce multiple cytokines." (PMID 30696484, 2019). "Thus, the enhancement of CD8+ T cell signatures possibly explains the reason why those mice receiving HMGN1/αCD4 treatment would be able to resist tumor progression and recurrence." (PMID 30696484, 2019). "HMGN1 serves as a potent immune stimulator that promotes dendritic cell (DC) activation and migration, and consequently polarizes Type 1 T helper cell-mediated immune responses, which enhance anti-tumor immunity in mice." (PMID 30696484, 2019). "However, the number of CD4+ T cells also increased in tumor after HMGN1/R848 or TheraVac treatment, which raises a possibility to cause immunosuppression by CD4+ T regulatory cells." (PMID 30696484, 2019). "Taken together, we concluded that HMGB1 and HMGN1 secreted by cancer cells may relate to recruitment of tumor infiltrating lymphocytes (TILs) in HNSCC." (PMID 30619746, 2018). "The failure of HMGN1 by itself to halt the growth of CT26 tumors might be due to the immunosuppressive tumor microenvironment that hindered the elimination of tumor cells by CT26-specific cytotoxic T lymphocytes (CTLs)." (PMID 29079801, 2017). "C57BL/6 mice bearing large EG7 tumors were successfully treated with four rounds of i.t. injection of R848 (10 μg/mouse/injection), HMGN1 (10 μg/mouse/injection), and anti-PD-L1 (10 μg/mouse/injection) within two weeks, with 4 of the 5 mice becoming tumor-free." (PMID 29079801, 2017). "Indeed, Hepa1-6 tumor bearing mice treated with a combination of HMGN1 and R848 showed significant retardation of tumor growth (& 5)." (PMID 28881713, 2017). "Thus, simultaneous administration of HMGN1 and R848 into tumor tissues activates tDCs and promotes potent protective anti-tumor immunity." (PMID 29079801, 2017). "The capacity of TheraVac to act as an antitumor vaccine is based on the activation of tDCs by the administered combination of R848 and HMGN1, which promotes tDC homing to draining lymph nodes for the induction of specific protective anti-tumor immune responses." (PMID 29079801, 2017).